TNF (tumor necrosis factor)
Diseases named in the same sentence as TNF in open-access papers (continued):
Sharing a sentence is not in itself a finding about the gene and the disease.
atherosclerosis (continued). "This is believed to be the precursor of lipid-laden foam cells and the beginning of atherosclerosis formation under the influence of pro-inflammatory cytokine release, such as interleukin(IL)-1, IL-6, tumor necrosis factor (TNF)-α, transforming growth factor-β (TGF-β)." (PMID 33860001, 2021). "Indeed, both osteoporosis and atherosclerosis have been linked to an overall inflammatory state and the levels of CRP, IL-6, and TNF-α directly correlated to the bone resorptive action of monocytes." (PMID 34610044, 2021). "Mechanistic evidence adds to these findings, since a number of cytokines implicated in the psoriatic and arthritic disease domains can contribute to atherosclerosis and metabolic impairments, including Th1 (TNF, IFNγ, and IL-12) and Th17 cytokines (IL-17, IL-22, IL-23, IL-6, and TNF)." (PMID 34527685, 2021). "Enrichment of target proteins by KEGG and GO demonstrated that target proteins are involved in body-related pathways, among which the IL-17 signalling pathway, fluid shear stress and atherosclerosis signalling pathway, and TNF signalling pathway enriched many targets." (PMID 33678123, 2021). "Macrophages take up oxidized LDL via scavenger receptors which, once inside the cell, induce cholesterol crystals that ultimately activate the inflammasome to release IL-1β and TNF cytokines, which are mediators of inflammation in both cancer and atherosclerosis 49-52." (PMID 34234868, 2021). "TNF-α is an essential cytokine involved in adaptive immunity during the process of atherosclerosis." (PMID 34071276, 2021). "In the present study, we tested the hypothesis that the ethanol extract of the flowers of C. tinctorius (ECT) could decrease the levels of vascular inflammation markers in response to TNF-α, upregulate HO-1, and thus, protect against atherosclerosis." (PMID 34961267, 2021). "The release of TNF-α, IL-6, and IL-10 can activate NF-кB to promote the production of inflammatory factors such as IL-8, which further aggravates the inflammatory reaction in the atherosclerosis process." (PMID 34568579, 2021). "Among the top 20 pathways (sorted by the degree value), there were mainly the IL-17 signaling pathway, the TNF signaling pathway, the Th17 cell differentiation pathway, the Toll receptor signaling pathway, the RA pathway, the fluid shear stress and atherosclerosis pathway, and so on." (PMID 34414237, 2021). "In the pathological process of atherosclerosis, the accumulation of cholesterol triggers the production of pro-inflammatory cytokines, such as tumor necrosis factor alpha (TNFα), and also leads to the aggregation of monocytes and differentiation into foam cells." (PMID 32013194, 2020). "TNF-α, a well-known proinflammatory cytokine, is actively involved in atherosclerosis." (PMID 32635347, 2020). "Furthermore, in the development of both RA and atherosclerosis, the same proinflammatory cytokines, i.e., interleukin (IL)-6 and tumor necrosis factor-alpha (TNF-α), are at work." (PMID 32228568, 2020). "Inflammation is caused as a response to repeated injury and involves the release of pro-inflammatory cytokines including tumor necrosis factor-α (TNF-α), interleukin (IL)-1, and IL-6, which promotes the progression of atherosclerosis, leading to plaque rupture and thrombosis." (PMID 32102321, 2020). "Moreover, inflammation plays an indispensable role in the progression of atherosclerosis, and inflammation-related pathways such as IL-17, TNF, toll-like receptor, T-cell receptor signaling pathways, were enriched among KEGG analysis." (PMID 32990315, 2020). "When evaluating the association between inflammatory markers and CIMT, a significant association with TNF-α was observed in the multivariate analysis, as the increase in IL1-β levels presented a greater chance of atherosclerosis with p-value close to significance." (PMID 31664319, 2020).
atherosclerosis (continued). "Thus, the vicious cycle formed between OxLDL and the inflammatory cytokines (TNF-α and IL-6) from macrophages in the subendothelial space results in a persistent inflammatory response that promotes atherosclerosis." (PMID 32752134, 2020). "TNF-α is an inflammatory marker and involved in the development of atherosclerosis." (PMID 33254709, 2020). "Moreover, TNF-α is closely related to atherosclerosis as it contributes to inflammation as well as promoting insulin resistance." (PMID 33254709, 2020). "Moreover, the endothelial hypoxia-inducible factor-1α promoted atherosclerosis and monocyte recruitment by upregulating miR-19a7, while TNF-α or IFN-γ or IL-4 suppressed IL-10 in B cells (from patients with atherosclerosis) via upregulating miR-19a expression." (PMID 32308549, 2020). "In contrast, endothelial cell-specific deletion of BRG1, achieved by lentivirus-mediated delivery of short hairpin RNA, resulted in anti-inflammatory effects via inhibiting inflammatory factors such as TNF-α in mice, which further ameliorated atherosclerosis in mice models." (PMID 33330454, 2020). "Concerning studies of atherosclerosis, OL could decreased serum lipids and tumor necrosis factor alpha (TNF-α) levels, which was accompanied by a down-regulation of monocyte chemostactic protein-1 and vascular cell adhesion molecule." (PMID 32050687, 2020). "At molecular and cellular levels, CD11b+DCs were found to promote the development of atherosclerosis by either exosome membrane-bound TNF-α that triggers inflammation in recipient endothelial cells, or interacting with circulating natural killer T cells (NKT) and Tregs." (PMID 32849502, 2020). "Inhibition of TNF-α reduces atherosclerosis in ApoE−/− mice." (PMID 32635347, 2020). "Moreover, ruxolitinib remarkably decreased plasma levels of IL-6, IL-1β, IFN-γ and TNF-α in rabbits with atherosclerosis." (PMID 32169038, 2020). "Specifically TNF-α and IL-6 are mentioned as being responsible for the reduction of NO production and, as a consequence, of endothelial dysfunction, which is considered a precursor to atherosclerosis and cardiovascular disease." (PMID 32486269, 2020). "IL-1β, IL-6, and TNF-α are soluble low-molecular-weight-proteins that mediate crosstalk between immune and nonimmune cells and have been implicated in atherosclerosis development and progression." (PMID 32485823, 2020). "Indeed, IL-17A, and moreover when combined with TNFα, induces endothelial dysfunction, vascular inflammation and atherosclerosis and finally promotes occurrence of CVE." (PMID 32983142, 2020). "In addition, previous reports have shown that the concentration of TNF-α was higher in the serum of patients with atherosclerosis, indicating a relevance of these findings in the context of this pathology." (PMID 32899258, 2020). "Therefore, inflammatory mediators such as interleukin (IL)-6, IL-8, and tumor necrosis factor-α (TNF-α) are commonly involved in the pathogenesis of RA-related atherosclerosis." (PMID 32824307, 2020). "A growing body of evidence suggests that anti-TNF-α therapy could effectively protect from the development of vascular diseases and atherosclerosis in particular." (PMID 33053859, 2020). "It is therefore speculated that the imbalance of IL-10 and TNF α may be relevant to the pathological development of atherosclerosis and heart failure." (PMID 32670064, 2020). "SOCS3, whose expression level increased continuously along with the elongation of feeding in ApoE−/− mouse aortas, is closely correlated with atherosclerosis progression because it plays a regulatory role in the expression and activation of IL-6, TNF-α, as well as other inflammatory cytokines." (PMID 32169038, 2020).
atherosclerosis (continued). "This study has shown that attenuation of cardiac remodeling, fibrosis, alleviation of the aortic root and coronary arteries atherosclerosis is dependent on the reduction of IL-1β, TNF-α, IL-6 cardiac mRNA expression, and nuclear factor kappa B (NF-κB) activation pathway in RVX pre-treated group." (PMID 33301454, 2020). "Tumor necrosis factor (TNF) is an important inflammatory cytokine in atherosclerosis." (PMID 33213432, 2020). "Increased TNF-α and IL-1β levels along with hyperglycemia helps to develop atherosclerosis." (PMID 30674322, 2019). "TNF-α is a polypeptide produced by the activated monocytes and lymphocytes, which can promote blood coagulation and inhibit fibrinolysis, and it is closely related to the occurrence and development of atherosclerosis." (PMID 31632272, 2019). "To develop a tractable endothelial cellular system to study the molecular mechanisms that contribute to the etiology of vascular diseases such as atherosclerosis and hypertension, we characterized the response of teloHAEC to the potent pro-inflammatory cytokine TNFα." (PMID 31287004, 2019). "These pro-inflammation proteins include IL-1β, IL-6, tumor necrosis factor α (TNFα), interferon γ (IFNγ), complement proteins, C-reactive protein (CRP), etc., which are implicated in the pathogenesis and progression of atherosclerosis and intravascular thrombosis." (PMID 31068769, 2019). "Further functional assays indicated that miR-30-5p could decrease the secretion of proinflammatory cytokine TNF-α to modulate the pathogenesis of atherosclerosis." (PMID 31354385, 2019). "Because our in vitro data demonstrate that HLP inhibited TNFα-induced VSMC migration and proliferation, in vivo results indicate that HLP can effectively improve HFD-promoted atherosclerosis in rabbits via decreasing TNF-α secretion to confirm the anti-atherosclerotic effect of HLP." (PMID 31817413, 2019). "Based on our previous studies on the ability of (R)-DOI to prevent vascular-related cell and tissue inflammation induced by TNF-α, which is a key pro-inflammatory cytokine in atherosclerosis and vascular inflammation, via 5-HT2A receptor activation we propose the following model." (PMID 31530895, 2019). "A study analyzing the human arterial tissue proteomics identified several vascular and plasma biomarkers related to early atherosclerosis including TNF-α, insulin receptor, PPARα, and PPARγ protein networks, predictors of both development and site of atherosclerosis and CVD." (PMID 31354915, 2019). "We have shown that B cell-derived TNF-α augments macrophage production of TNF-α in atherosclerosis." (PMID 31998318, 2019). "CD4+ T cell exosomes enhanced cholesterol accumulation and induced the production of the proinflammatory cytokine TNF-α in cultured human monocytes, which suggests that T cell exosomes might play a role in the pathogenesis of atherosclerosis." (PMID 31615107, 2019). "Taken together, our findings indicate the anti-TNF-α effects of HLP on VSMC could likely contribute to its protection against atherosclerosis and other cardiovascular disorders." (PMID 31817413, 2019). "TNFα and PPARγ are important modulators of metabolism, inflammation, and atherosclerosis." (PMID 31275366, 2019). "The present study shows that TNF-α stimulates NF-κB-dependent biogenesis of miR-155, the levels of which were substantially upregulated in both mouse atherosclerotic arteries and samples from patients with atherosclerosis and preeclampsia." (PMID 30765689, 2019). "Inflammation after vascular injury has been considered an important contributor to atherosclerosis.Tumor necrosis factor (TNF)-α, a proinflammatory cytokine, has been reported to be a modulator of leukocyte adhesion and migration in vascular inflammatory diseases." (PMID 30191468, 2019).
atherosclerosis (continued). "In addition, resveratrol has been observed to enhance autophagy for the alleviation of vascular endothelial inflammation in an atherosclerosis model, protecting HUVECs from inflammation induced by TNF-α." (PMID 30744138, 2019). "The Th1 cytokines, especially IFN-γ and TNF-α, play an important role in atherosclerosis." (PMID 31330988, 2019). "This leads to the release of an array of pro-inflammatory cytokines, such as interleukin-1-alpha (IL-1α), IL-1β, IL-6, tumor necrosis factor-alpha (TNF-α) and matrix metalloproteinases (MMPs), which further exacerbates atherosclerosis by promoting immune cell infiltration." (PMID 31357404, 2019). "Thus, it appears that TNFα is an important inflammatory cytokine during the progression of atherosclerosis." (PMID 31735914, 2019). "Our results indicated that C8:0 reduced body fat, improved the lipid profiles, suppressed inflammatory cytokine production, downregulated aortic TLR4, MyD88, NF-κB, TNF-α, IKKα, and IKKβ mRNA expression, and alleviated atherosclerosis in the apoE−/− mice (P < 0.05)." (PMID 31182969, 2019). "TNFα induces a pro-inflammatory process in endothelial cells, altering function of endothelial and vascular smooth muscle cells, which is crucially involved in the progression of atherosclerosis and heart failure." (PMID 30479572, 2018). "Although inconsistency in results between studies mainly due to different study design and different outcome measures, there are data suggesting that biologic therapies, in particular tumor necrosis factor-α inhibitors (TNFα-i), improve surrogate markers of subclinical atherosclerosis." (PMID 30619884, 2018). "We used two inflammatory proteins, HMGB1 and TNF-α, which induce early atherosclerosis." (PMID 29561847, 2018). "Studies in ApoE−/− mice indicate that supplementation with curcumin leads to less macrophage infiltration in atherosclerosis plaque, reduced aortic NF-κB activation, reduced levels of IL-1B and TNF-α, and reduced expression of the adhesion molecules ICAM-1 and VCAM-1." (PMID 30518065, 2018). "TNF-α is a cytokine involved in the pathogenesis and progression of atherosclerosis." (PMID 29849875, 2018). "TNF-α and IFN-γ enhance macrophage activation, leading to high levels of pro-inflammatory cytokines and mediators, and hence, can cause extensive damage to the host leading to atherosclerosis and thrombosis." (PMID 29337902, 2018). "Among them, inflammation is a well-known cause of cardiovascular events; indeed, atherosclerosis is an inflammatory process; numerous inflammatory molecules including hs-CRP, IL-6, IL-1β and TNF-α are elevated in patients with myocardial infarction or unstable angina." (PMID 29439738, 2018). "The important role of interferon-γ and TNF-α in the pathogenesis of atherosclerosis is well known." (PMID 30662365, 2018). "Additionally, we injected inflammatory proteins directly into the endothelium of the vessel, which is the site of HMGB1 and TNF-α participation in early mechanisms of atherosclerosis." (PMID 29561847, 2018). "Moreover, CD14++CD16+ monocytes secrete high levels of tumor necrosis factor-α and interleukin-1β, which are involved in the pathogenesis and progression of atherosclerosis." (PMID 28789689, 2017). "During atherosclerosis, stimulation by tumour necrosis factor-alpha (TNF-α) increases the binding of intracellular NFKB in cells associated with arterial blood vessels, creating SEs and a redistribution of BRD4 near genes that are upregulated during an inflammatory response." (PMID 28378740, 2017). "The reduction of MMP-2 and -9, and TNF-α by mesoglycan could have a positive role in contrasting atherosclerosis progression." (PMID 28272312, 2017). "Together, these data indicate that TNF-α may represent a promising target to reduce atherosclerosis." (PMID 29038791, 2017).
atherosclerosis (continued). "Tumor necrosis factor-alpha may play a direct role in the development of atherosclerosis through induction of ICAM-1, MCP-1, P-selectin, and E-selectin in endothelial and vascular smooth muscle cells resulting in endothelial cell apoptosis." (PMID 29187850, 2017). "Furthermore, the p38 pathway is implicated in cholesterol ester accumulation in MΦ and the development of atherosclerosis, since its activation plays an essential role in the production of inflammatory cytokines (TNF-α, IL-6)." (PMID 28173800, 2017). "TNF-α is an important inflammatory factor in early atherosclerosis." (PMID 29029426, 2017). "Thus there is a forward feedback loop during atherosclerosis: TNF-α stimulates the expression of miR-19a to suppress HBP1 and subsequently elevate MIF production, which in turn increases TNF-α secretion." (PMID 28935967, 2017). "Release of cytokines such as TNF-alpha and interleukin-2 during inflammation or stress leads to endothelial dysfunction disruption of atheromatous plaques and hypercoagulability, all leading to acceleration of atherosclerosis." (PMID 28270112, 2017). "Among them, some research has shown that IL-6 in inflammatory response may mediate artery atherosclerotic plaque vulnerability and burst, and TNF-α may promote atherosclerosis formation." (PMID 27563892, 2016). "Because our IHC data indicated that HCD can effectively promote atherosclerosis in rabbits via inducing TNF-α secretion, we further used TNF-α to induce proliferation and migration of VSMCs and then treated them with acarbose to confirm the effect of acarbose on atherosclerosis." (PMID 27924924, 2016). "To date, the underlying mechanism of TNF-α inhibition by adalimumab on sub-clinic atherosclerosis is not fully comprehended." (PMID 27467817, 2016). "Besides adhesion molecule expression, increased endothelial permeability with increased leucocyte invasion and augmented lipid uptake into the diseased vessel wall is another well-known process in early atherosclerosis and likewise promoted by TNF-α." (PMID 27467817, 2016). "The ever‐exposed drug model was chosen for the primary analysis because it was hypothesized that blockade of TNF likely influences all stages of atherosclerosis progression and subsequent development of cardiovascular events over the medium to long term." (PMID 26749043, 2016). "The crucial role of TNF-α in atherosclerosis is well supported by scientific evidence." (PMID 27467817, 2016). "Human monocytes exhibit dysregulated inflammatory responses with aging consisting of both elevated (i.e. increased TNF‐α) and impaired (i.e. decreased IL‐1β) responses, both of which could contribute to atherosclerosis." (PMID 27135421, 2016). "This binds to target mRNAs including tumor necrosis factor-α (TNF-α), C-reactive protein and interleukin-1 receptor-associated kinase-1 (IRAK1), which affect vascular damage responses and inflammation-related atherosclerosis in the development of stroke." (PMID 27164084, 2016). "Hansson describes, for example, the development of an inflammatory cascade in atherosclerosis, involving, but not limited to, inflammatory cytokines (e.g. tumor necrosis factor alpha (TNF-α), interleukin-1 (Il-1)), interleukin-6 (Il-6), and acute-phase reactants (e.g. C-reactive protein (CRP))." (PMID 27270459, 2016). "SAA has been widely considered not only as a biomarker of inflammation and atherosclerosis, but also as a proinflammatory mediator that could directly stimulate the production of series of cytokines, such as TNF-α, IL-1β, MCP-1, and Lp-PLA2." (PMID 27006946, 2016). "Moreover, high concentrations of plasma-soluble TNF-α are considered a key feature in cardiovascular diseases, such as atherosclerosis, CAD and MI, therefore it is also a marker for recurrent coronary events." (PMID 26751459, 2016). "Various growth factors, including PDGF-BB and TNF-α, are upregulated in atherosclerosis." (PMID 25784946, 2015).